CA5B (carbonic anhydrase 5B)
Description:
Mitochondrial carbonic anhydrase that catalyzes the reversible conversion of carbon dioxide to bicarbonate/HCO3.
Synonyms: CA-VB; CAVB
Tractability: Small molecule: an approved drug acts on it; a high-quality ligand is known; it belongs to a druggable protein family. PROTAC: ubiquitination databases record sites on it; its protein half-life has been measured; a small molecule that binds it is known.
Target class: Enzyme; Lyase
Gene: Protein-coding gene on chromosome X (15,688,830 to 15,788,411, forward strand). Ensembl gene ENSG00000169239.
Subcellular location: Mitochondrion
Subcellular location (Human Protein Atlas): Mitochondria
Pathways (Reactome):
Metabolism: Reversible hydration of carbon dioxide
Gene Ontology:
Molecular function: carbonate dehydratase activity; protein binding; zinc ion binding
Cellular component: mitochondrion; cytoplasm; mitochondrial matrix
Homologues: Orthologues: chimpanzee CA5B (100% identical), macaque CA5B (98% identical), rabbit CA5B (91% identical), mouse Car5b (89% identical), rat Car5b (89% identical), guinea pig CA5B (88% identical), dog CA5B (75% identical), tropical clawed frog ca5b (63% identical), zebrafish ca5a (52% identical), Caenorhabditis elegans cah-5 (31% identical), Caenorhabditis elegans cah-6 (27% identical), Drosophila melanogaster CAH6 (26% identical), and 11 more. Paralogues in human: CA5A (58% identical), CA2 (44% identical), CA7 (43% identical), CA13 (41% identical), CA1 (39% identical), CA3 (37% identical), CA8 (30% identical), CA10 (27% identical), CA14 (27% identical), CA12 (27% identical), CA9 (26% identical), CA11 (26% identical), and 2 more.
Diseases named in the same sentence as CA5B in open-access papers:
CA5B is named in the same sentence as 14 diseases in open-access papers, as found by Europe PMC text mining. Sharing a sentence is not in itself a finding about the gene and the disease. The quoted sentences say what the papers report.
breast carcinoma (2 papers, 2023 to 2024). "Yet, CA5B is associated with improved survival in HER2-enriched breast cancer (HR = 0.827)." (PMID 37098526, 2023).
leukemia (1 paper, 2026). A malignant (clonal) hematologic disorder, involving hematopoietic stem cells and characterized by the presence of primitive or atypical myeloid or lymphoid cells in the bone marrow and the blood. "Importantly, using a drug-repurposing approach, we found that inhibition of CA5B, PPP3CA, and PP2A by acetazolamide, tacrolimus, and LB-100, respectively, showed high toxicity toward KMT2A::AFF1+ leukemic blasts and reduced leukemia burden in vivo." (PMID 42038742, 2026).
lung adenocarcinoma (1 paper, 2021). A carcinoma that arises from the lung and is characterized by the presence of malignant glandular epithelial cells. "The heatmap reveals that HNRNPLL|53258|AT, CA5B|98313|ES, MEGF6|315|ES, and CDKN2A|86000|AP may have positive effects on lung adenocarcinoma while BEST3|23330|AT, TTC39C|44852|AP, AP2B1|40327|AD, LETM2|83399|AT, and MKL1|62348|AP can have adverse effects." (PMID 35004299, 2021).
cancer (2 papers, 2023 to 2024). A tumor composed of atypical neoplastic, often pleomorphic cells that invade other tissues. "The mitochondrial CA5A and CA5B show relatively similar expression levels across cancer epithelial cells, endothelial cells, cancer-associated fibroblasts, and immune cells (T cells, B cells, and myeloid cells)." (PMID 37098526, 2023).
respiratory diseases (1 paper, 2023). "For example, genes associated with respiratory diseases and cell proliferation (CA5B, ID2, CARD14 and TRIM29) were significantly altered." (PMID 36673815, 2023). "In Konwar’s study, CA5B was shown to be associated with respiratory diseases." (PMID 36673815, 2023).
CA5B also shares sentences with these, for which no sentence is quoted: tumor (3 papers); atherosclerosis (1); AV block (1); cardiac conduction disease (1); COVID-19 (1); Hyperammonemia (1); infectious disease (1); Obesity (1); pancreatic cancer (1).